SCN4A (sodium voltage-gated channel alpha subunit 4)
Diseases named in the same sentence as SCN4A in open-access papers (continued):
Sharing a sentence is not in itself a finding about the gene and the disease.
Myotonia (continued). "The defining features of SCN4A skeletal muscle channelopathies are myotonia and/or muscle weakness." (PMID 25348630, 2014). "Non-dystrophic hereditary myotonia may also occur with variants in SCN4A, including paramyotonia congenita, hyperkalaemic periodic paralysis (HYPP) and sodium channel myopathies or potassium aggravated myotonia in humans, and HYPP in horses." (PMID 39765607, 2024). "Three patients from families with an SCN4A-associated non-dystrophic myotonia had also BrS." (PMID 34722688, 2021). "Skeletal muscle channelopathies associated to SCN4A gene mutations indeed represent a continuum in the clinical spectrum, as also supported by the high frequency of episodes of paralysis in PMC and the relative high incidence (50%) of myotonia in Hyper/NormoPP." (PMID 32849172, 2020). "The p.I141V mutation in SCN4A and SCN5A, as well as its homologous p.I136V mutation in SCN9A, are interesting examples of mutations that have been linked to inherited hyperexcitability myotonia, exercise-induced polymorphic ventricular arrhythmias and erythromelalgia, respectively." (PMID 25741286, 2015). "We describe a Chinese family affected by both CMT1A and myotonia with concomitant alterations in both the PMP22 and SCN4A genes." (PMID 34996390, 2022). "Additionally, in a different study, the authors investigated whether BrS can be part of the clinical phenotype associated with SCN4A variants, and whether patients with BrS present with non-dystrophic myotonia or periodic paralysis and related gene mutations." (PMID 34722688, 2021). "Of those who trialed medications, 56.5% (n = 13) of CLCN1 patients, 66.7% (n = 10) of SCN4A patients, and 8.3% (n = 2) of DMPK patients had tried more than one medication for myotonia." (PMID 32670189, 2020). "The only exception was a patient displaying a neonatal SCN4A and showing a pattern III, suggestive of SCM, but with clear clinical paradoxical myotonia; a similar discrepancy has already been reported." (PMID 32849172, 2020). "Interestingly, baseline AMPK activation levels were also higher in Scn4aM1592V/+ muscles, confirming that the rise in AMPK activation levels is not unique to draggen muscles and could be a generalized feature of Scn4a mouse models showing myotonia and hind-limb dragging attacks." (PMID 25348630, 2014). "Nondystrophic myotonias (NDMs) are a group of hereditary muscle diseases characterized by myotonia, muscle stiffness, and a nondystrophic phenotype, which are caused predominantly by mutations in CLCN1 or SCN4A." (PMID 34996390, 2022). "Myotonia at onset was more frequent in patients with CLCN1-myotonia (85.7%) than in patients with SCN4A-myotonia (50%) (p = 0.003); periodic paralysis was only reported in patients with SCN4A-myotonia (20%) (p = 0.008)." (PMID 33263785, 2021). "Other SCN4A mutations are responsible for SCM, which can be distinguished from PMC by the lack of both paradoxical myotonia and episodes of flaccid paralysis." (PMID 34208776, 2021). "Weakness was reported in a similar proportion of individuals with non-dystrophic myotonias, 65.2% (n = 15) of individuals with CLCN1 variants, and 69.2% (n = 9) SCN4A variants." (PMID 32670189, 2020). "In previous work, we segregated the draggen mutation from the HD transgene, cloned it and characterized it as a model of SCN4A channelopathies, leading to non-dystrophic myotonia and intermittent attacks of hind-limb immobility followed by total recovery." (PMID 29509900, 2018). "However, at least for NDM6, the patient showed a similar phenotype (including age of onset, no weakness or muscle pain, generalized myotonia, etc.)as patients carrying only the CLCN1 mutation in heterozygosity or the SCN4A mutation." (PMID 33670307, 2021). "Interestingly, the prevalence of stiffness was the only feature that differed significantly among patients with non-dystrophic myotonias, with more individuals with CLCN1 variants reporting this symptom than individuals with SCN4A variants." (PMID 32670189, 2020).
Myotonia (continued). "We reviewed T1-weighted and STIR (short-tau-inversion-recovery) 3T MRI sequences of lower limb muscles at thigh and calf level in 21 patients with genetically confirmed non-dystrophic myotonia: 11 with CLCN1 mutations and 10 with SCN4A mutations, and 19 healthy volunteers." (PMID 23810313, 2013). "Recent studies indicate that, unlike DM1, either CLCN1 or SCN4A acts as genetic modifiers in DM2 patients since mutations/polymorphisms in these genes may contribute to exaggerated phenotype with more severe muscle stiffness and myotonia." (PMID 34234810, 2021). "Contrary to patients with periodic paralysis, myotonia may be absent on EMG in SCN4A-related CMS." (PMID 30808424, 2019). "In patients suspected of having a non-dystrophic myotonia, the most expeditious, and cost-effective approach is panel testing including CLCN1 and SCN4A sequencing." (PMID 32670189, 2020). "Nevertheless, the severity of myotonia especially at lower limbs and the general stiffness were not satisfactorily explained by the diagnosis of PMC based on clinical symptoms and genetic analysis of SCN4A, hence the involvement of a second genetic “player,” namely CLCN1 gene, was hypothesized." (PMID 36081873, 2022).
periodic paralysis (48 papers, 2008 to 2026). "Similar gender-specific differences in symptom severity have also been observed in other neuromuscular diseases, such as SCN4A mutation-associated hypokalemic periodic paralysis, suggesting a potential area for further investigation of CMT2Z." (PMID 39464795, 2024). "For example, the SCN4A gene is associated with an actionability score of 9 in the hyperkalemic periodic paralysis (severity score at 1), compared to a score of 11 in the congenital myasthenic syndrome type 16 (severity score at 3)." (PMID 35955641, 2022). "The other knock-in strain models hypokalaemic periodic paralysis via another Scn4a mutation (R669H)." (PMID 25348630, 2014). "There are a number of clinically classified types of muscle channelopathies caused by mutations in the SCN4A gene, including: potassium-aggravated myotonia, paramyotonia congenita, hyperkalaemic periodic paralysis and hypokalaemic periodic paralysis." (PMID 25348630, 2014). "The first Scn4a knock-in model carries the mouse equivalent of the most common human hyperkalaemic periodic paralysis mutation (M1592V)." (PMID 25348630, 2014). "In recent years two knock-in mouse models of periodic paralysis have been generated to study the effects of Scn4a mutations on skeletal muscle function." (PMID 25348630, 2014). "The low penetrance of hypokalaemic periodic paralysis due to SCN4A mutations in females is also likely to be due to the effect of oestrogens." (PMID 23820649, 2013). "Hyperkalemic Periodic Paralysis and Paramyotonia Congenita are rare forms of Periodic Paralysis that are also associated SCN4A mutations that cause gain-of-function abnormalities in the sodium channel resulting in prolonged muscle cell excitation." (PMID 18939979, 2008). "For example, studies have reported that vitamin D deficiency is frequently observed in patients with familial hypokalemic periodic paralysis with SCN4A gene mutations, although the exact mechanism remains unclear." (PMID 39703113, 2024). "The NaV1.4channel is expressed in skeletal muscle, and mutations in its α-subunitgene (SCN4A) lead to a number of congenital disorders of themusculoskeletal system, such as myotonia, paramyotonia, hyperkalemic andhypokalemic periodic paralysis, myasthenia gravis, and myopathy." (PMID 33959393, 2021). "SCN4A variants are described as cause of autosomal-dominant myotonia and periodic paralysis." (PMID 33789662, 2021). "In addition, it has been suggested that attenuated slow inactivation is common for SCN4A variants associated with periodic paralysis." (PMID 28330959, 2017). "However, there is accumulating evidence that other mutation sites in CACNA1S and SCN4A, and even new ion channel mutations may induce periodic paralysis." (PMID 41800133, 2026). "In contrast to SCN4A-CMS, gain-of-function variants in hyperkalemic periodic paralysis, hypokalemic periodic paralysis, potassium-aggravated myotonia congenita, and paramyotonia congenita shift the fast inactivation curve toward depolarized states." (PMID 36835142, 2023). "Five families with PPP included: hypokalemic periodic paralysis type 1 (HypoPP1, CACNA1S, 1/5), hypokalemic periodic paralysis type 2 (HypoPP2, SCN4A, 2/5), normokalemic periodic paralysis (NormoPP, SCN4A, 1/5), and Andersen-Tawil syndrome (ATS, KCNJ2, 1/5)." (PMID 33345742, 2021). "SCN4A mutations leading to periodic paralysis or nondystrophic myotonia have been found located throughout every domain and segment of this channel." (PMID 38609989, 2024). "HypoPP is the most frequent form of periodic paralysis in humans, with a prevalence rate of approximately 1 in 100,000 live births.About 60% of patients are classified as HypoPP-1 because they carry variants of the CACNA1S gene; while 20% patients are classified as HypoPP-2 with SCN4A gene variants." (PMID 38609989, 2024).
periodic paralysis (continued). "We obtained a Japanese nationwide case series of 119 index patients (108 men and 11 women) clinically suspected of periodic paralysis, and a gene panel analysis, targeting CACNA1S, SCN4A, and KCNJ2 genes, was conducted." (PMID 36779057, 2023).
paramyotonia congenita (34 papers, 2007 to 2025). "One patient diagnosed with paramyotonia congenita had a novel heterozygous SCN4A c.2143G > A (p.A715T) variant." (PMID 38055022, 2024). "Variants of the SCN4A gene encoding human Nav1.4 (hNav1.4), expressed in the skeletal muscle, are associated with autosomal-dominantly inherited muscle diseases such as sodium channel myotonia, paramyotonia congenita, hyperkalemic periodic paralysis, and hypokalemic periodic paralysis." (PMID 39164360, 2025). "Three of them had mutations in the SCN4A gene causing a paramyotonia congenita." (PMID 36401657, 2023). "SCN4A encodes the skeletal muscle voltage-gated sodium channel Nav1.4 and is a well recognized cause of channelopathies, including hyperkalemic and hypokalemic periodic paralysis, paramyotonia congenita and sodium channel myotonia with rare cases of SCN4A-related CMS reported." (PMID 39051439, 2024). "Paramyotonia congenita (PMC), sodium channel myotonia (SCM), and hyperkalemic periodic paralysis (HyperPP) are all caused by dominant gain-of-function variants in SCN4A." (PMID 32670189, 2020). "Loss-of-function variants of SCN4A cause CMS, whereas gain-of-function variants of SCN4A cause hyperkalemic periodic paralysis, hypokalemic periodic paralysis, potassium-aggravated myotonia congenita, and paramyotonia congenita." (PMID 36835142, 2023). "The NDMs include myotonia congenita (MC) due to mutations in the skeletal muscle chloride channel gene CLCN1, paramyotonia congenita (PMC) and sodium channel myotonia (SCM), both of the latter are caused by mutations in the skeletal muscle sodium channel gene SCN4A encoding Nav1.4." (PMID 34140924, 2021). "Sodium channel myotonia (SCM) and paramyotonia congenita (PMC) are rare non-dystrophic muscle disorders with muscle hyperexcitability caused by gain-of-function mutations in the voltage-gated skeletal muscle sodium channel gene (SCN4A)." (PMID 40843127, 2025).
HyperPP (33 papers, 2008 to 2025). "Mutations in the sodium channel (SCN4A) gene are responsible for HyperPP, whereas mutations in two other genes lead to HypoPP, specifically SCN4A (HypoPP2) or the skeletal muscle calcium channel (CACNA1S) gene (HypoPP1)." (PMID 41527600, 2025). "Among them, 3 families with HypoPP and 1 family with HyperPP carried mutations in the SCN4A gene (31 patients), while 1 carried a mutation in the CACNA1S gene (7 patients)." (PMID 38609989, 2024). "Mutations of SCN4A that are associated with HyperPP affect the gating behavior of this channel and produce gain-of-function defects characterized by impaired inactivation and/or enhancement of activation." (PMID 38609989, 2024). "HypoPP1 is caused by mutations of CaV1.1 channel gene (CACNA1S), while HypoPP2, NormoPP, and HyperPP are caused by mutations of NaV1.4 channel gene (SCN4A)." (PMID 33345742, 2021). "This disorder, also called hyperkalemic periodic paralysis (HyperPP), is associated with autosomal dominant mutations in SCN4A." (PMID 27141276, 2016). "Although muscle fat infiltration was seen in all types of PP, patients with SCN4A mutations were found to have the most severe fat infiltration, suggesting that the allelic disorders HyperPP and HypoPP II may be particularly susceptible to PP myopathy." (PMID 39777323, 2024). "HyperPP is caused by mutations in the skeletal muscle voltage-gated sodium gene (SCN4A)." (PMID 39777323, 2024). "Hyperkalemic periodic paralysis (hyperPP) is characterized by high serum potassium concentrations (hyperkalemia) in individuals affected and is also caused by pathogenic mutations in the SCN4A gene." (PMID 38672523, 2024). "HyperPP and NormoPP are associated with mutations in the NaV1.4 channel gene (SCN4A)." (PMID 33345742, 2021). "In veterinary medicine, a SCN4A-related equine form of HyperPP has been reported (OMIA 000785-9796)." (PMID 34828398, 2021). "In humans, genetic confirmation of known pathogenic variants in SCN4A-related PMC and HyperPP, and KCNJ2-related Andersen–Tawil syndrome-related, is included in the diagnosis of these disorders." (PMID 34828398, 2021). "SCN4A mutations could also lead to other kinds of diseases, specifically SCM, PMC, HypoPP2 and hyperkalemic periodic paralysis (HyperPP)." (PMID 32407401, 2020). "Likewise, in human medicine, patients with phenotypical characteristics of PMC, HyperPP, and Andersen–Tawil syndrome were found not to present pathogenic variants in the SCN4A or in KCNJ2, suggesting further genetic heterogeneity." (PMID 34828398, 2021).
channelopathies (30 papers, 2014 to 2025). "Most of the skeletal muscle channelopathies arise from de novo or autosomal dominant mutations in the SCN4A gene, which encodes the α-subunit of the Nav1.4 channel." (PMID 34572327, 2021). "Our case supports the hypothesis that SCN4A variants can lead to fetal death with hydrops and highlights the broadening spectrum of SCN4A channelopathy." (PMID 39164360, 2025). "Thus, although SCN4A related channelopathies are mostly caused by missense mutations, there is increasing evidence that little in-frame deletions may play a role." (PMID 36081873, 2022). "The most common channelopathy was myotonia congenita, which was associated with variants in the CLCN1 gene in 10 of the 11 patients, and one was associated with a variant in the SCN4A gene." (PMID 40883749, 2025). "Mutations in genes encoding the subunit of L-type voltage-dependent calcium channel Cav1.1 (CACNA1S) and skeletal muscle sodium voltage-gated channel Nav1.4 (SCN4A) are responsible for channelopathies observed in HPP." (PMID 39897933, 2025). "The hypomorph nature of several SCN4A LoF mutations and the dosage effect suspected to occur in SCW suggest that such an approach would also be efficient for Nav1.4 channelopathies." (PMID 34671263, 2021). "Hypokalemic periodic paralysis is a genetically heterogeneous channelopathy that has been linked to mutations in genes encoding three ion channels CACNIAS, SCN4A, and KCNJ2 predominantly." (PMID 25893123, 2015). "By generating and characterizing a mouse model (‘draggen’) carrying the equivalent point mutation (I582V), they uncover novel pathological and metabolic features of SCN4A channelopathies." (PMID 25348630, 2014). "In addition, the SCN4A, SCN5A, and SCN10A genes that encode the skeletal muscle NaV1.4, the cardiac NaV1.5 and the PNS NaV1.8 channels, respectively, are associated with other channelopathies." (PMID 36891145, 2023). "In contrast to the situation observed for dominantly-inherited Nav1.4 channelopathies, no recurrent SCN4A mutations have been described for recessively-inherited Nav1.4 channelopathies, the reported mutations being private." (PMID 34671263, 2021). "Therefore, draggen mice offer a novel excellent model to study the role of tubular aggregates and vacuoles in the pathophysiology of SCN4A channelopathies." (PMID 25348630, 2014). "Their unspecific, predominantly myalgic phenotype was very consistent in all patients lacking most of the other typical features of SCN4A channelopathies." (PMID 28330959, 2017).
hypokalemic periodic paralysis (27 papers, 2014 to 2026). Hypokalemic periodic paralysis (hypoPP) is characterized by episodes of muscle paralysis lasting from a few to 24-48 hours and associated with a fall in blood potassium levels. "SCN4A mutations can cause muscle diseases such as congenital myotonia, myasthenic syndrome, and hypokalemic periodic paralysis." (PMID 37510298, 2023). "Another class of heterozygous SCN4A mutations allow an anomalous leakage of ions through the voltage sensor of the channel, distinct from the sodium-conducting pore, and cause hypokalemic periodic paralysis." (PMID 32117035, 2020). "Hypokalemic periodic paralysis (HypoPP) is a rare genetic disease associated with mutations in CACNA1S or SCN4A encoding the voltage-gated Ca2+ channel Cav1.1 or the voltage-gated Na+ channel Nav1.4, respectively." (PMID 37139703, 2023). "Mutations in the CACNA1S, RYR1, SCN4A gene have been reported to be associated with hypokalemic periodic paralysis (HOKPP) in humans." (PMID 35158718, 2022). "Hypokalemic periodic paralysis is an autosomal dominant, rare disorder caused by variants in the genes for voltage-gated calcium channel CaV1.1 (CACNA1S) and NaV1.4 (SCN4A)." (PMID 34120654, 2021). "Myotonia congenita and hypokalemic periodic paralysis type 2 are both rare genetic channelopathies caused by mutations in the CLCN1 gene encoding voltage-gated chloride channel CLC-1 and the SCN4A gene encoding voltage-gated sodium channel Nav1.4." (PMID 32407401, 2020). "Of all individuals meeting the diagnostic criteria for hypokalemic periodic paralysis, approximately 60 % have mutations in the calcium channel CACNA1S gene, 20 % in the sodium channel SCN4A gene and 3.5 % in the potassium KCNJ18 gene." (PMID 27682153, 2016). "Hypokalemic periodic paralysis (HypoPP) is a rare skeletal muscle channelopathy, most often caused by mutations in CACNA1S or SCN4A." (PMID 41551049, 2026). "Hypokalemic periodic paralysis (hypoPP) is an autosomal dominant, rare disorder with a prevalence of 1:100,000 that is caused by variants in the gene coding for calcium channel CaV1.1 (CACNA1S OMIM 170,400) or less frequently in the gene for sodium channel NaV1.4 (SCN4A OMIM 613,345)." (PMID 34120654, 2021).